CLCF1 (cardiotrophin like cytokine factor 1)
Diseases named in the same sentence as CLCF1 in open-access papers (continued):
Sharing a sentence is not in itself a finding about the gene and the disease.
Hypertension (1 paper, 2021). The presence of chronic increased pressure in the systemic arterial system. "CAD was set as a dependent variable, while age, CLCF1 protein and mRNA levels, and hypertension were set as covariables, and a multiple logistic regression analysis (Enter method) was performed." (PMID 33430863, 2021). "Therefore, hypertension was set as a dependent variable, while age, CLCF1 mRNA, and CLCF1 protein levels were set as covariables, after which a multiple logistic regression analysis (Enter method) was performed." (PMID 33430863, 2021). "The results suggested that age was a risk factor for hypertension (p < 0.05), while the mRNA levels and protein expression of CLCF1 were not correlated with hypertension (p > 0.05)." (PMID 33430863, 2021). "Considering the differences in age and the incidences of gastrointestinal diseases and hypertension among different groups, we analyzed the effects of gastrointestinal disease, hypertension, and CAD on the expression level of CLCF1 in PBMCs." (PMID 33430863, 2021).
memory impairment (1 paper, 2022). "As a result, 3 DEmRNAs from CCI with memory impairment model rats (ATF3, C1QC, and CD68) and 13 DEmRNAs from SNI and CCI models (ADAMTS2, BCL6B, CLCF1, RBP1, and TPBG, among others) overlapped with SNI and CCI models, respectively." (PMID 35547819, 2022).
neuroblastoma (1 paper, 2018). Neuroblastoma (NB) is the most common solid, extracranial childhood tumor. "To exclude possibility that the VLDL-effect is linked to a characteristic of the Ba/F3 pro-B cell line, we investigated the effect of the lipoproteins on the binding of CLCF1 to IMR-32 human neuroblastoma cells or the 3T3-L1 mouse pre-adipocytes both expressing CNTFR5,14." (PMID 29507344, 2018).
neurofibroma (1 paper, 2017). An intraneural or extraneural neoplasm arising from nerve tissues and neural sheaths. "Inhba, Cxcl2, Il1b, Clcf1, Lif, and Ccl5 were up-regulated in human neurofibroma SCs, and may justify further study." (PMID 28256556, 2017).
Obesity (1 paper, 2025). Accumulation of substantial excess body fat. "This indicates that targeting CLCF1 signaling might be an effective treatment for obesity-related metabolic issues." (PMID 40969371, 2025). "Knocking out CLCF1 in BAT boosts its activation and improves glucose and lipid metabolism, protecting mice from diet-induced obesity." (PMID 40969371, 2025).
ovarian carcinoma (1 paper, 2024). A malignant neoplasm originating from the surface ovarian epithelium. "Our results showed that CLCF1 or CNTFR knockdown did not affect DDP-induced cytotoxicity in ovarian cancer cells." (PMID 39256356, 2024).
peripheral nerve injury (1 paper, 2025). Injury to a peripheral nerve. "Phosphorylation of STAT3 is a known consequence of peripheral nerve injury, and particularly noteworthy in the context of our study: several of the mediators we identified as up-regulated with nerve injury in mouse mural cells are cytokines which activate the JAK/STAT pathway (Il6, Lif and Clcf1)." (PMID 40381746, 2025).
postmenopausal osteoporosis (1 paper, 2021). Metabolic disorder associated with fractures of the femoral neck, vertebrae, and distal forearm. "The expression level of CLCF1 in PBMCs was observed to decrease in women with postmenopausal osteoporosis in a whole gene chip analysis." (PMID 33430863, 2021). "In this study, we sought to investigate the involvement of CLCF1 in this context, based on a previous work in which we demonstrated that CLCF1 could be a responding gene correlated with therapeutic effects on postmenopausal osteoporosis." (PMID 33430863, 2021).
renal dysplasia (1 paper, 2015). Renal dysplasia is a form of renal malformation in which the kidney(s) are present but their development is abnormal and incomplete. "A case of renal dysplasia associated with cold sweating syndrome and potential deficiency of CLCF-1/CRLF-1 has been reported." (PMID 26146641, 2015).
renal failure (1 paper, 2015). "B-cell responses to CLCF-1 may also be important in progression of FSGS to fibrosis and renal failure." (PMID 26146641, 2015).
rheumatoid arthritis (1 paper, 2016). A chronic, systemic autoimmune disorder characterized by inflammation in the synovial membranes and articular surfaces. "One could imagine that cytokines or other soluble factors produced in rheumatoid arthritis (possibly CLCF-1)?" (PMID 27088031, 2016).
Sepsis (1 paper, 2025). Sepsis is defined as life-threatening organ dysfunction caused by a dysregulated host response to infection. "Dot plot visualization further confirmed these trends at the gene level, with C3, SERPING1, and HLA-A/B/C being notably upregulated in Astrocyte 2 under sepsis conditions, while EMP1, CLCF1, and PTGS2—representing A2 features—were similarly elevated." (PMID 41030458, 2025).
tuberculosis (1 paper, 2019). A chronic, recurrent infection caused by the bacterium Mycobacterium tuberculosis. "It would therefore be interesting to: (i) assess CLCF1 expression following BCG administration, and (ii) test whether its co-administration with BCG generates an optimal protective innate immunity against tuberculosis." (PMID 31552057, 2019).
tumor (36 papers, 2016 to 2026). "CLCF1 levels in cancer-associated fibroblasts play a role in promoting tumor cell stemness and facilitating the infiltration and polarization of tumor-associated neutrophils in hepatocellular carcinoma." (PMID 40169936, 2025). "CLCF1, which was made by CAFs, caused tumor cells to make more CXCL6 and TGF-β, which worked on tumor cells to make them more stem-like and on TANs to cause N2 polarization." (PMID 37007004, 2023). "Recently, Song et al86 elucidated an intricate crosstalk among CAFs, HCC cells, and tumor-associated neutrophils triggered by CAF-derived CLCF1 cytokines." (PMID 36708970, 2023). "In hepatocellular carcinoma, CLCF1 levels in cancer-associated fibroblasts (CAFs) promote tumor cell stemness as well as the infiltration and polarization of tumor-associated neutrophils (TANs)." (PMID 35265072, 2022). "CLCF1 may potentially serve two important roles as a promising target linked to immunotherapy outcomes: suppressing tumor development and synergizing with immunotherapy." (PMID 38152333, 2023). "For instance, CAFs-derived cardiotrophin-like cytokine factor 1 (CLCF1) engages ciliary neurotrophic factor receptor (CNTFR) on tumor cells, promoting the release of CXCL6 and TGF-β." (PMID 41445734, 2025). "CAFs can then induce M2 macrophage and N2 neutrophil polarization both through direct secretion of TGFβ and through secretion of cardiotrophin-like cytokine factor 1 (CLCF1), which can induce expression of TGFβ in tumor cells." (PMID 38254801, 2024). "Clinically, high levels of CLCF1 expression have been found to be correlated with aggressive tumor behaviors and worse clinical outcomes." (PMID 36835352, 2023). "In liver cancer, CAFs crosstalk with immune cells through CCL2, CLCF1, or endosialin release, favoring tumoral infiltration of MDSCs, N2 neutrophils, or M2 macrophages with resultant tumor propagation." (PMID 36708970, 2023). "This study highlighted the clinical significance of CAF-derived cardiotrophin-like cytokine factor 1 (CLCF1) signaling in CAF-mediated direct crosstalk with tumor cells and indirect interaction with TANs within the HCC TME." (PMID 36835352, 2023). "miR-30a-5p can reverse the resistance of sorafenib in HCC cells by directly targeting CLCF1, thereby exerting an anti-tumor effect." (PMID 35911380, 2022). "In Univariate Cox Regression analysis and Kaplan-Meier survival analysis, tumor patients with higher CLCF1 expression tended to experience a worse prognosis." (PMID 35265072, 2022). "The factors (IGFBP5, CLCF1 and IL6) reported to be secreted by CAFs indeed showed significantly higher expression in the high-risk group, suggesting that fibroblasts in the tumor microenvironment of LUAD likely contribute to the poor outcome in LUAD patients." (PMID 35711936, 2022). "As a promising target related to immunotherapy outcomes, CLCF1 has the potential of directly inhibiting tumor growth and synergism with immunotherapy." (PMID 35265072, 2022). "With regard to the nomogram, it was also an excellent predictive evaluation model and was superior to tumor grade or CLCF1 expression level alone in predicting OS." (PMID 35265072, 2022). "A recent study demonstrated that CLCF1, an interleukin-6 (IL-6) family cytokine involved in neurodevelopment, regulates the tumor immune milieu and has potential as a prognostic marker and therapeutic target in patients with glioma associated with phosphatase and tensin homolog (PTEN) mutations." (PMID 40169936, 2025). "Various CAF-secreted solute factors, such as IL-6, IL-33, TGF-β, stromal cell derived factor-1 (SDF-1), and CAF-derived cardiotrophin-like cytokine factor 1 (CLCF1) produce tumor-promoting signals that mediate the signal transduction of tumor cells or other cells in the TME." (PMID 37217855, 2023). "Overall, blockade of CLCF1/CNTFR signalling could be a novel therapeutic opportunity for LUAD and potentially for other tumour types in which CLCF1 is present in TME." (PMID 35055176, 2022).
tumor (continued). "Abrogation of CLCF1 through eCNTFR–Fc appears most effective in tumours driven by oncogenic KRAS." (PMID 35055176, 2022). "CAF-derived factors such as cardiotrophin-like cytokine factor 1 (CLCF1) increased expression of TGF-β and chemokine ligand 6 (CXCL6) secretion from tumor cells." (PMID 36831295, 2023). "Using a murine model engrafting CAFs-HCC cells followed by tail-vein infusion of human neutrophils, they showed that CLCF1 or CNTFR depletion abrogated neutrophil recruitment and tumor proangiogenic growth triggered by CAFs." (PMID 36708970, 2023). "The interaction of CLCF1 with its receptor on HCC cells (CNTFR) contributes to N2 neutrophil infiltration and tumor propagation." (PMID 36708970, 2023). "CAFs can also secrete the cytokines cardiotrophin-like cytokine factor 1 (CLCF1) and interleukin 6 (IL6) to directly stimulate the growth of tumor cells." (PMID 35711936, 2022). "CAFs secrete cardiotrophin-like cytokine factor 1 (CLCF1) inducing the production of CXCL6 and transforming growth factor-β (TGF-β) by tumor cells deriving TANs polarization into N2 phenotype and promoting tumor stemness." (PMID 36613878, 2022). "CLCF1 increased chemokine CXCL6 and TGF-β secretion in tumour cells, activated the ERK1/2 signalling of CAFs to produce more CLCF1, thus forming a positive feedback loop to accelerate HCC progression." (PMID 35055176, 2022). "A recent study showed that CAF-derived cardiotrophin-like cytokine factor 1 (CLCF1) induces TAN-N2 polarization by increasing the expression of CXCL6 and TGF-β in tumor cells, thereby accelerating tumor progression." (PMID 35784290, 2022). "On multivariate COX analysis, the WHO grade, age, IDH status, and CLCF1 expression were independent prognostic factors in the TCGA dataset; while in the CGGA dataset, tumor grade, age, 1p/19q status, and CLCF1 expression were independent prognostic factors." (PMID 35265072, 2022). "CAF-derived cardioctonutrient-like cytokine 1 (CLCF1) has been found in studies to stimulate the release of TGF-β and CXCL6 in tumor cells, consequently increasing tumor stem cell development in HCC-TME." (PMID 34869376, 2021). "In HCC-TME, CAF-derived cardioctonutrient-like cytokine 1(CLCF1) increases the secretion of CXCL6 and TGF-β in tumor cells, thereby promoting tumor stem cell growth." (PMID 34869376, 2021). "Specifically, CLCF1 released by CAFs induced the production of CXCL6 and TGF-β by tumor cells, which acted on tumor cells themselves, promoting their stemness, and on TANs, driving their N2 polarization." (PMID 34200529, 2021). "Elevated CLCF1 and LIF levels may lead to STAT3 activation, which enhances tumor cell proliferation, including HCC." (PMID 37777158, 2023). "Furthermore, N2, or protumorigenic polarization of neutrophils within the tumor can be induced through CAF-derived cardiotrophin-like cytokine factor 1 (CLCF1), which upregulates CXCL6 and TGF-β on tumor cells." (PMID 36010899, 2022). "Additionally, cardiotrophin-like cytokine factor 1 (CLCF1), a cytokine that belongs to the IL-6 superfamily, can be secreted by CAFs to induce the secretion of (C-X-C motif) ligand 6 (CXCL6) and TGF-β in HCC, which subsequently promote tumor cell stemness in an autocrine manner." (PMID 35971182, 2022). "Interestingly, CRLF1 does not require CLCF1 or GP130 in this novel role, although the studies were performed only in a tumour-derived cell model system." (PMID 35055176, 2022).
cancer (23 papers, 2010 to 2025). A tumor composed of atypical neoplastic, often pleomorphic cells that invade other tissues. "In lung cancer, CLCF1 acts as a protumorigenic factor in cancer-associated fibroblasts." (PMID 40169936, 2025). "Upon further investigation, it was found that CLCF1 acts as a cytokine that promotes cancer cell stemness in HCC." (PMID 40755769, 2025). "TGF-β is an important player in the dialogue between cancer and stroma cells favoring the secretion of cytokines, like CLCF1 (CAF-derived cardiotrophin-like cytokine factor 1)." (PMID 38138981, 2023). "Aberrant expression of CLCF1 in human cancers was found by comparing the pan-cancer data extracted from TCGA and GETx databases." (PMID 35265072, 2022). "Accordingly, factors (IGFBP5, CLCF1 and IL6) reported to be secreted by cancer-associated fibroblasts (CAFs) showed higher expression level in the high-risk group." (PMID 35711936, 2022). "CAFs-derived cardiotrophin-like cytokine factor 1 (CLCF1) stimulates HCC cancer cells to release TGF-β and C-X-C motif chemokine ligand 6 (CXCL6)." (PMID 36115852, 2022). "In a cohort of HCC clinical samples, the authors highlighted the role of the cardiotrophin-like cytokine factor 1 (CLCF1)-CXCL6/TGF-β axis in the regulation of cancer stemness, alongside the concomitant recruitment of “N2” TANs, contributing to the poor prognosis of HCC patients." (PMID 34200529, 2021). "However, the role of CLCF1 in mediating cell-cell interactions in cancer has remained unclear." (PMID 38562778, 2024). "Studies have shown that CLCF1 produced by CAFs can stimulate TGF-β1 and CXCL6 secretion by cancer cells, thereby increasing the stemness of cancer cells and activating the ERK1/2 signaling pathway in CAFs." (PMID 38694506, 2024). "Cancer cells from growing ribociclib-resistant tumors modify the behavior of immune regulating myeloid cells, through production of diverse communications including CSF1, CLCF1, FGF, and TGF family members and interleukins 5/11/12." (PMID 40032842, 2025). "Solute factors secreted by CAFs, such as IL-6, IL-33, TGF-β, CAF-derived cardiotrophin-like cytokine factor 1 (CLCF1), and stromal cell derived factor-1 (SDF-1), can produce cancer-promoting signals and participate in the signal transduction of cancer cells and other cells within the TME." (PMID 39595654, 2024). "The scientists found that the cardiotrophin-like cytokine factor 1 (CLCF1)-CXCL6/TGFβ-axis, as well as the contemporaneous recruitment of N2 TANs, had a role in the control of cancer stemness in a cohort of HCC clinical samples, leading to the poor prognosis of HCC patients." (PMID 37007004, 2023). "Cancer cells of growing ribociclib-resistant tumors used a diverse set of M2-like differentiation stimulating communication pathways as shown by a range of markers: CSF1, CLCF1, several FGFs (1/2/7/17/18/23), the TGF family member GDF9, interleukin 5/11/12, MADCAM1 and PLAU." (PMID 40032842, 2025).
infection (3 papers, 2020 to 2024). The state of being infected such as from the introduction of a foreign agent such as serum, vaccine, antigenic substance or organism. "For instance, we detected an upregulation of the Cardiotrophin-like cytokine factor 1 (Clcf1) and Amphiregulin (Areg) in the Vγ6+ cells during infection, which is predicted to engage with their cognate receptors Cntfr and Egfr, respectively." (PMID 37644007, 2023). "Cardiotrophin-like cytokine factor 1 (Clcf1) was one of the genes found to be consistently upregulated by the infection with all four strains of T. cruzi." (PMID 32626662, 2020). "Notably, the genes induced by the infection were enriched in multiple immune activation pathways, including cytokine-cytokine receptor interaction (e.g., Il22, Tnfrsf9 and Clcf1), JAK-STAT signaling pathway (e.g., Stat3), and chemokine signaling pathway (e.g., Ccr7) 33–35." (PMID 39013884, 2024).
genetic diseases (1 paper, 2020). "Eventually, data from human genetic disorders identified cytokine receptor-like factor 1 (CRLF1)/cardiotrophin-like cytokine factor 1 (CLCF1) as cholinergic differentiation factor in human sweat glands." (PMID 32930881, 2020). "The mutational inactivation of CRLF1 and leukemia inhibitory factor receptor (LIFRβ) in human genetic diseases identified CRLF1/CLCF1 to be essential for cholinergic differentiation of sweat gland innervation." (PMID 32930881, 2020).
renal disease (1 paper, 2015). "The results are consistent with our postulate that CLCF-1 may contribute to human renal disease, specifically FSGS in patients with recurrence after renal transplant." (PMID 26146641, 2015). "We have identified CLCF-1 in the plasma of patients with FSGS who experience recurrence of proteinuria and renal disease in the allograft after transplantation." (PMID 26146641, 2015).
retinopathy (1 paper, 2018). "Intraocular injection of either VLDL or CLCF1 in a mouse model of oxygen-induced retinopathy showed a beneficial effect on both retinal neovascularization and vaso-obliteration." (PMID 29507344, 2018).
CLCF1 also shares sentences with these, for which no sentence is quoted: lung adenocarcinoma (2 papers); C. perfringen infection (1); endometriosis (1); gastrointestinal disease (1); glomerulopathies (1); immune disorders (1); ischemia (1); ischemic stroke (1); Kyphoscoliosis (1); nephrotic syndrome (1); nonalcoholic steatohepatitis (1); Osteopenia (1); psoriasis (1); Schwartz-Jampel type 2 syndrome (1); skin squamous cell carcinoma (1).